BRAF (B-Raf proto-oncogene, serine/threonine kinase)
Diseases named in the same sentence as BRAF in open-access papers (continued):
Sharing a sentence is not in itself a finding about the gene and the disease.
ganglioglioma (continued). "Additionally, the genetic alterations responsible for BRAF p.V600 wildtype gangliogliomas are largely unknown, as is the spectrum of any additional cooperating gene mutations or copy number alterations." (PMID 29880043, 2018). "In the two gangliogliomas that progressed after initial resection of unknown extent, sequencing analysis that was performed on the recurrent tumors demonstrated FGFR2-INA fusion in one and BRAF p.V600E mutation in the other." (PMID 29880043, 2018). "However, our study shows that a small subset of pathologically-confirmed gangliogliomas can harbor this identical combination of CDKN2A homozygous deletion and BRAF p.V600E mutation, indicating that this genetic pattern is not entirely specific to pleomorphic xanthoastrocytomas." (PMID 29880043, 2018). "However, such genetic abnormalities were not harbored by those gangliogliomas in which we were unable to show a KIAA1549-BRAF fusion or BRAF:p.V600E mutation." (PMID 24529209, 2014). "BRAF V600E mutations, which are of therapeutic importance, are present in around 30% of gangliogliomas, DNETs and DIA/DIG, with glioneuromas in the diencephalic region showing a higher rate of BRAF positivity." (PMID 40013208, 2025). "Crucially, PXA’s molecular signature, characterized by MAPK pathway activation predominantly via BRAF V600E and the CDKN2A/B deletion, provides a robust tool to differentiate it from close differentials such as ganglioglioma." (PMID 37998600, 2023). "We found evidence of neoplastic cell dual perturbations to BRAF/MEK and PI3K/AKT/mTOR pathways and identified ganglioglioma gene regulatory networks (resembling those present during neuroectoderm neural development) and associated immune cell states." (PMID 36966348, 2023). "Most gangliogliomas show molecular evidence of activation of the mitogen-activated protein kinase (MAPK) pathway, with the BRAF V600E as the most common alteration, and the most common chromosomal alteration is the gain of chromosome 7." (PMID 36290809, 2022). "The wide dispersion in mutation frequencies and the absence of BRAF V600E mutations in later studies is probably due to poor interobserver agreements regarding discrimination of DNT from other glioneuronal tumors such as ganglioglioma and probably improper classification of some tumors as DNET." (PMID 31181803, 2019). "The revised PD of ganglioglioma in these scenarios was grounded by the presence of dysmorphic ganglion cells and the absence of a combined BRAF and CDKN2A/B molecular signature." (PMID 37998600, 2023). "All three BRAF V600E tumours lacked typical histopathological features of ganglioglioma, especially ganglion cells." (PMID 35836307, 2022). "BRAF V600E mutations are found in 20–35% of non-PXA, non-ganglioglioma pLGG and confer a worse prognosis and relative insensitivity to chemotherapy." (PMID 31466300, 2019). "For example, BRAF p.V600E has been observed in 25%–35% of adult and pediatric gangliogliomas, whereas other BRAF genetic alterations and KIAA1549-BRAF and FAM131B-BRAF fusions have also been observed in low-grade gliomas, the former fusion having been identified in gangliogliomas." (PMID 29434027, 2018). "In those 13 gangliogliomas lacking identifiable BRAF alteration, nine contained other genetic alterations predicted to activate the MAP kinase signaling pathway." (PMID 29880043, 2018). "A third unexpected morphology of large, dysplastic ganglion-like cells (GCs), as in ganglioglioma, previously reported in DMG/K27M, with H3-K27M expression but lacking BRAF mutations, was present in F10 pons focally, demonstrating the metaplastic potential of these neoplastic cells." (PMID 32680567, 2020). "Interestingly, the two gangliogliomas with pseudopapillary features, which are negative for SLC44A1-PRKCA fusion, were BRAF mutation immunopositive." (PMID 26671581, 2015).
ganglioglioma (continued). "None of the gangliogliomas in this cohort showed genetic alterations in components of this pathway, except for one ganglioglioma that recurred after gross total resection and harbored a subclonal PTEN missense mutation (in addition to BRAF p.V600E mutation and CDKN2A homozygous deletion)." (PMID 29880043, 2018).
Lynch syndrome (103 papers, 2010 to 2026). An autosomal dominant hereditary neoplastic syndrome characterized by the development of colorectal carcinoma and a high risk of developing endometrial carcinoma, gastric carcinoma, ovarian carcinoma, renal pelvis carcinoma, and small intestinal carcinoma. "In contrast, CRCs associated with Lynch syndrome attributable to a GPV in MLH1 rarely have the BRAF V600E variant." (PMID 41214301, 2026). "Diagnosis should include a serum measurement of carcinoembriyogenic antigen (CEA), mismatch repair or microsatellite instability testing, and evaluation of genetic mutations such as RAS and BRAF, particularly in the context of potential Lynch syndrome." (PMID 40004690, 2025). "BRAF mutations are detected in nearly 40% of sporadic MSI‐H CRC, whereas few BRAF mutations have been observed in Lynch syndrome patients." (PMID 39073010, 2024). "By combining MSI testing with BRAF V600E mutation calling, testing for Lynch syndrome can be performed with a single assay." (PMID 39300198, 2024). "In this respect, tyrosine kinase translocations are similar to the BRAF p.V600E mutation, which is a validated marker for the exclusion of microsatellite-unstable CRCs from Lynch syndrome germline testing." (PMID 37686416, 2023). "BRAF p.V600E is tested not only for prognostic stratification and evaluation of risk of Lynch syndrome, but also to allow for treatment with recently approved targeted therapy." (PMID 37350948, 2023). "In creating guidelines for CRC molecular biomarkers, the ASCP, CAP, AMP, and ASCO recommended that patients with dMMR tumors with loss of MLH1 receive BRAF p.V600 mutational analysis to evaluate for risk of Lynch syndrome." (PMID 36980565, 2023). "Patients with MLH1 promoter hypermethylation had higher scores than patients with Lynch Syndrome, as a result of the known association between BRAF mutations and MLH1 hypermethylation and the high score given to BRAF mutations in the model." (PMID 33494280, 2021). "In additional, detection of BRAF mutation is useful to distinguish sporadic MSI CRCs from Lynch syndrome, and the presence of BRAF mutation is associated with worse prognosis in metastatic CRC (mCRC) patients." (PMID 32095377, 2020). "In EO mCRC patients, MSI more frequently resulted from Lynch syndrome, which was usually mutually exclusive from BRAF V600E mutation." (PMID 33194656, 2020). "Of 204 patients with MLH1‐ and MLH1/PMS2‐deficient tumours, 199 (97·5 per cent) underwent reflex BRAF mutational testing to screen for Lynch syndrome, of whom 58 (29·1 per cent) were BRAF wild‐type." (PMID 30511046, 2018). "KRAS mutations were found in 22 (31%) patients, whereas mutation in BRAF was noted in only one case of genetically confirmed Lynch syndrome." (PMID 19935791, 2010). "BRAF V600E mutation was identified, and germline testing excluded Lynch syndrome." (PMID 41346621, 2025). "Additionally, microsatellite instability with confirmed Lynch syndrome is rarely associated with BRAF positivity." (PMID 40162154, 2025). "BRAF mutation testing plays an important role in Lynch syndrome identification after MSI testing." (PMID 41310156, 2025). "Several mechanisms were proposed for pMMRd without gMMRd, including hypermethylation of the MLH1 promoter (considered a variant of Lynch syndrome), BRAF V600E somatic mutation (considered sporadic cancer), and Lynch-like syndrome if the previous two are absent." (PMID 39001404, 2024). "This population is heterogeneous, encompassing special cases of Lynch syndrome resulting from hypermethylation of the MLH1 promoter BRAF V600E somatic mutation that is considered sporadic cancer, and “Lynch-like syndrome (LLS)” if the previous two alterations are absent." (PMID 39001404, 2024).
Lynch syndrome (continued). "We have also verified that BRAF mutations are less frequent among Middle Easterners, which may have implications for Lynch syndrome screening practices in Middle Eastern populations." (PMID 38139338, 2023). "Lynch syndrome occurs in approximately only 1% of BRAF p.V600E mutated CRC." (PMID 37350948, 2023). "It is known that BRAF V600E mutation hardly ever occurs in MSI-H CRCs due to Lynch syndrome." (PMID 33854094, 2021). "Across this series of dMMR Lynch syndrome spectrum cancers, double somatic genetic alterations explained 23% (n = 19) of cases overall and 49% (19/39) of those lacking causal germline variants, MLH1 promoter hypermethylation, and BRAF V600E, also known as Lynch-like syndrome." (PMID 34397043, 2021). "Hence, evaluation of mutations in the BRAF gene can be a cost-effective method to separate the MSI sporadic cases from the inherited Lynch syndrome cases." (PMID 31939059, 2020). "In contrast, BRAF V600E mutation is very rare in CRC patients with Lynch syndrome." (PMID 29127628, 2019). "Therefore, it was suggested that assessment of BRAF V600E mutation can be used to triage patients for mismatch repair (MMR) genetic testing to differentiate MLH1-deficient sporadic CRC from Lynch syndrome caused by germ-line MLH1 mutations." (PMID 29127628, 2019). "Responses were independent RAS/BRAF mutation status, PD-L1 expression or Lynch syndrome history." (PMID 31139574, 2019). "Furthermore, after excluding likely sporadic cases via BRAF or hypermethylation analysis, a significant subset of these individuals harbors a germline mutation consistent with Lynch syndrome—confirming that younger age of onset is a strong predictor of hereditary disease." (PMID 40244260, 2025). "It is important to note the differences between Lynch syndrome-associated CRC and sporadic MSI-H CRC, such as the frequency of BRAF V600E variants and methylation status." (PMID 41214301, 2026). "Current Australian guidelines recommend genetic testing for Lynch syndrome in all patients whose tumors are both MMR-deficient and BRAF-WT, because these patients have a higher risk of germline mutations in the MMR genes." (PMID 38139338, 2023). "A therapeutic effect was observed irrespective of the degree of PD-L1 expression, the presence of the BRAF/KRAS mutations, or the presence of Lynch syndrome." (PMID 37599324, 2023). "The recommended paradigm for screening of Lynch syndrome is to examine for BRAF p.V600E and/or MLH1 promoter methylation to select dMMR CRC for further germline testing." (PMID 37350948, 2023). "Since BRAF V600E gene mutations are rarely found in the Lynch syndrome-related CRC, BRAF screening in MSI-H/dMMR CRC helps to distinguish sporadic MSI-H/dMMR tumor or Lynch syndrome." (PMID 36230726, 2022). "The great majority of spontaneous MSI-H CRCs, in contrast to Lynch syndrome tumours, are considered to develop in CIMP-H sessile serrated adenomas with BRAF mutation through methylation-associated inactivation MLH1." (PMID 35010119, 2022). "BRAF-mt in high MSI (MSI-H) CRC usually indicates sporadic CRC whereas patients with MSI-H BRAF wild type (BRAF-wt) CRC should be tested for Lynch Syndrome." (PMID 34940086, 2021). "A therapeutic effect was observed irrespective of the degree of PD-L1 expression, the presence of the BRAF/KRAS mutations, and the presence of Lynch syndrome." (PMID 31286289, 2020). "The 4th case had phenotypic features of Lynch syndrome, and the BRAF V600E result would have been inconsequential in clinical practice." (PMID 31647837, 2019). "BRAF and KRAS were mutated in 16% and 35% of patients, respectively; 28% of patients had PD-L1 positive tumors and 31% had Lynch syndrome." (PMID 28635639, 2017). "They suggested the screening model using immuno-histochemistry (IHC) of MMR protein with methylation the MLH1 promoter and then BRAF analysis as the standard protocol for Lynch syndrome screening." (PMID 24759670, 2013).
Lynch syndrome (continued). "After limiting to studies that excluded Lynch syndrome, the associations between early-onset CRC and BRAF (0.77, 0.64-0.92) and APC mutation (0.81, 0.67-0.97) were attenuated, while an inverse association with PIK3CA mutation was also observed (0.88, 0.78-0.99)." (PMID 38737895, 2024). "Because the BRAF V600E mutation is related to sporadic CRC patients but excludes Lynch syndrome, it is a key biomarker in distinguishing between the two etiologies." (PMID 36980565, 2023). "Although the absence of BRAF mutation does not completely exclude the risk of Lynch syndrome, the presence of a BRAF mutation would strongly favor a sporadic etiology." (PMID 36980565, 2023). "Methylation of the MLH1 promoter region which is typically seen in sporadic MSI-H CRC, but not in Lynch syndrome, is strongly associated with the BRAF V600E mutation." (PMID 37962682, 2023). "Approximately 10-15% of CRCs are dMMR, among which 80% are sporadic owing to MLH1 promoter hypermethylation or v-Raf murine sarcoma viral oncogene homolog B1 (BRAF) mutations, whereas 20% are due to autosomal dominant germline mutations, termed Lynch syndrome (LS)." (PMID 37664303, 2023). "Since biomarker testing was mostly relevant for patients considered for anti-EGFR therapy (KRAS, NRAS) or younger patients (MMR testing for Lynch syndrome or BRAF testing for prognostication), it is possible that more young and fit patients with mCRC were tested." (PMID 37071802, 2023). "The somatic inactivation of mismatch repair genes is strongly associated with BRAF V600E mutation (60%), which is practically absent in Lynch syndrome." (PMID 36819812, 2022). "Patients with mutations resulting in absence of the MMR gene MLH1 protein product and normal BRAF status were considered to be at high risk of Lynch syndrome (LS)." (PMID 34998373, 2022). "In these CRCs developed in Lynch syndrome patients BRAF mutations are absent, while KRAS are frequent (about 40%)." (PMID 29652830, 2018). "BRAF V600E mutations are overrepresented in dMMR tumors and can be used to rule out Lynch syndrome, while KRAS mutations (in codons 12 or 13) are inversely correlated with dMMR status." (PMID 30005666, 2018). "Somatic BRAF mutations can be useful to rule out Lynch syndrome, because they frequently occur in sporadic MSI CRCs, caused by MLH1 promoter methylation." (PMID 29849630, 2018). "Despite having wild-type BRAF, this tumor is sporadic and unrelated to Lynch syndrome." (PMID 28840050, 2017). "Molecular phenotyping identified loss of mismatch-repair protein immunostaining for PMS2, microsatellite instability, a lack of MLH1 promoter methylation, and lack of BRAF mutation suggestive of Lynch syndrome." (PMID 27965933, 2016). "In fact, presence of the BRAF V600E mutation in CRC essentially excludes Lynch syndrome, with the exception of rare cases associated with PMS2 germline mutation." (PMID 26875156, 2016). "Methylation of the MLH1 promoter region that is typically seen in sporadic MSI-H CRC, but not in Lynch syndrome, is strongly associated with the BRAF V600E gene mutation." (PMID 26875156, 2016). "Unfortunately, data on sporadic mismatch repair deficiency, germeline-mutation prompted Lynch Syndrom, BRAF/KRAS/NRAS mutations, or any family history can not be ascertained from the SEER data." (PMID 27464835, 2016).